LEP (leptin)
Diseases named in the same sentence as LEP in open-access papers (continued):
Sharing a sentence is not in itself a finding about the gene and the disease.
Cachexia (continued). "However, low levels of leptin have been measured in patients with both chronic inflammatory conditions and cachexia, raising the possibility that repression of leptin reflects biological compensation in response to these conditions." (PMID 18070349, 2007). "Notably, leptin levels do not consistently correlate with COPD-associated cachexia, questioning its role as a direct therapeutic target for managing weight loss in these patients." (PMID 40283443, 2025). "Low leptin concentrations could be considered a result, not a cause of cachexia, which significantly relates to adipose atrophy and low fat mass in cachexia." (PMID 26508820, 2015). "Hormonal signals involved in cachexia include insulin and insulin growth factor 1 (IGF-1), leptin, ghrelin, melanocortins, neuropeptide Y and growth hormone." (PMID 35326490, 2022). "Although patients with cachexia have significantly lower leptin levels, this reduction does not lead to an increase in appetite or a decrease in energy expenditure." (PMID 41373779, 2025). "Furthermore, age-related leptin resistance can amplify systemic inflammation, metabolic dysregulation, and muscle wasting in older COPD patients, exacerbating cachexia and reducing quality of life." (PMID 40283443, 2025). "Patients with cachexia had significantly higher levels of fatty acid-binding protein 3 (FABP3), follistatin-like 1 protein (FSTL−1), interleukin 6 (IL 6), and interleukin 8 (IL 8), while leptin concentrations in the peripheral blood were significantly lower." (PMID 39411315, 2024). "Considering that cachexia may occur in the early stages of ALS, our results might suggest that leptin is a potential biomarker of adipose tissue wasting, and subsequently, the muscle atrophy and depletion of fat stores clinical features in ALS." (PMID 34638645, 2021). "In the last ten years, several molecules have been proposed as biomarkers of cachexia including pro-inflammatory cytokines (e.g., interleukine 6, IL-6 and tumor necrosis factor alpha, TNF-α), hormones (e.g., leptin and ghrelin) and peptides such as C-terminal agrin fragment (CAF)." (PMID 34445710, 2021). "Decreased levels of leptin have been demonstrated in cancer patients with cachexia compared to those without cachexia and healthy controls." (PMID 25400234, 2014). "Median levels of IL-6, TNF-α, and leptin at 6:30 AM didn't differ significantly between the cohorts with and without cachexia, and the observed trends in level fluctuations were similar to those previously reported." (PMID 25411961, 2014). "In the 16 male patients, median levels of IL-6, TNF-α, and leptin at 6:30 AM didn't differ significantly between the cohorts with and without cachexia." (PMID 25411961, 2014). "Leptin concentrations during the day remained lower in the cohort with cachexia than in that without." (PMID 25411961, 2014). "Leptin levels are significantly decreased in cancer cachexia patients compared to both cancer noncachexia and healthy controls." (PMID 22518191, 2012). "Leptin release is inhibited in HF patients with cachexia when compared to noncachectic subjects." (PMID 35326490, 2022). "In patients with cancer cachexia, the plasma levels of leptin were lower than in patients without cachexia, which could be due to reduced fat mass in these patients." (PMID 26508818, 2015). "This deregulation of the physiological feedback may explain why a decrease in leptin does not increase appetite or lower energy expenditure in patients with cancer cachexia." (PMID 25400234, 2014). "In agreement with the results of previous studies, median IL-6 and TNF-α levels in the cohort with cachexia were nearly double those in the cohort without, and leptin levels in the cohort with cachexia were around half those in the cohort without, albeit without statistical significance." (PMID 25411961, 2014). "Besides, median IL-6 and TNF-α levels appeared higher and leptin concentration appeared lower in the cachexia group, albeit without statistical significance." (PMID 25411961, 2014).
Cachexia (continued). "Functional status, anthropometry, and serum markers of nutrition and inflammation, including leptin and CRP, in seventy elderly patients versus controls revealed that those with the lowest functional status and highest frailty indices displayed features of cachexia." (PMID 22518191, 2012). "Circulating leptin levels were found independent of the TNF-α system, and they were regulated physiologically even in the presence of cachexia in patients with COPD." (PMID 36139468, 2022). "Regardless of the reason, this hyperleptinemia in both cachectic and noncachectic CHF patients suggests that leptin-mediated decrease in appetite and food intake is not particularly important in the development of CHF-induced cachexia." (PMID 22518191, 2012). "Although leptin, a key regulator of body weight and energy balance, is generally lower in COPD patients compared to healthy controls, it correlates primarily with BMI and body composition rather than inflammation or cachexia-related markers." (PMID 40283443, 2025). "Taken together, the data suggests that leptin's role in this setting is not entirely related to body weight regulation and that the decreased appetite and increased energy expenditure seen in CHF-induced cachexia are more likely due to other factors." (PMID 22518191, 2012).
type 1 diabetes (60 papers, 2001 to 2025). "Collectively, these results have indicated a therapeutic value of physiological leptin on the cardiovascular burden associated with Type 1 diabetes, possibly mediated via partial or complete restoration of altered gene expression patterns of fatty acid metabolism and lipogenesis." (PMID 34064112, 2021). "However recent studies demonstrate that Leptin monotherapy improves several of the metabolic imbalances caused by insulin deficient type 1 diabetes in rodents by CNS dependent mechanism." (PMID 21687731, 2011). "Leptin levels are low in newly diagnosed patients with type 1 diabetes and increase after the institution of insulin therapy." (PMID 40888596, 2025). "In the current study, leptin and bioLEP concentrations were assessed in children with type I diabetes and healthy children." (PMID 37670877, 2023). "Leptin infusion into the ventricles of type 1 diabetes mice inhibited the expression of glucagon, consistent with the phenotype of peripheral hyperleptinemia." (PMID 37400922, 2023). "Many studies have suggested that leptin can be used as an antidiabetic drug or in addition to insulin therapy in patients with insulin-dependent diabetes." (PMID 37670877, 2023). "In our recent studies, macrosomic foetuses of mothers with type 1 diabetes had higher insulin, IR, and leptin levels." (PMID 34210228, 2021). "Here, the authors report that leptin action is mediated by inhibition of the heightened activity of arcuate GABA neurons in murine models of type 1 diabetes through restoring nutrient sensing." (PMID 33976218, 2021). "The present study used a lentiviral vector for leptin gene therapy to treat type 1 diabetes for the first time." (PMID 34947993, 2021). "In the present study, the efficacy of leptin treatment to reduce blood glucose levels was investigated in model systems of type 1 diabetes." (PMID 31743040, 2020). "An important implication of these observations is that the therapeutic potential of leptin as an additional treatment in patients with type 1 diabetes is probably limited." (PMID 31743040, 2020). "The possibility to use leptin therapeutically for lowering glucose levels in patients with type 1 diabetes has attracted interest." (PMID 31743040, 2020). "In a broader perspective, the present results weaken the prospects of using leptin in the routine treatment of type 1 diabetes." (PMID 31743040, 2020). "Data concerning leptin levels in this group of patients vary, and exogenous insulin therapy leads to elevated leptin levels in patients with type 1 diabetes." (PMID 26273677, 2015). "In contrast to our results, some authors reported that plasma leptin and adiponectin were increased in patients with type 1 diabetes." (PMID 24719626, 2013). "A previous study conducted among women with type 1 diabetes reported that plasma leptin levels are independently related to reduced renal function." (PMID 22666590, 2012). "Evidence has shown that leptin could substitute for insulin to control blood sugar fluctuations in patients with type 1 diabetes." (PMID 37373070, 2023). "For example, the systemic injection of leptin in a non-obese rodent model of insulin-deficient type 1 diabetes, results in normalization of glycemia following a glucose challenge." (PMID 35454388, 2022). "Moreover, insulin infusion increases plasma leptin concentration in humans, and rodents with type 1 diabetes exhibit significantly reduced leptin levels." (PMID 34084149, 2021). "Importantly, as a consequence of the leptin resistance demonstrated here, the therapeutic potential of leptin treatment in type 1 diabetes is likely limited." (PMID 31743040, 2020). "A possibility to use leptin in the treatment of patients with type 1 diabetes has been discussed." (PMID 31743040, 2020). "Accordingly, the use of leptin as a treatment for type 1 diabetes has been suggested." (PMID 31743040, 2020).
type 1 diabetes (continued). "However, leptin exerts important effects on HR regulation in insulin-dependent diabetes that require an intact pituitary." (PMID 29190687, 2017). "Umbilical cord leptin concentration correlates with adiposity in human neonates and babies born to obese mothers, and to those with gestational or type 1 diabetes, have higher umbilical leptin concentrations at delivery compared with those born to lean, nondiabetic mothers (43, –, 45)." (PMID 26479186, 2016). "Furthermore, the researchers showed that, in a mouse model of type 1 diabetes, leptin was as effective as insulin in controlling blood sugar; nevertheless the mechanism of action is far from clear." (PMID 24639883, 2014). "Recently, the researchers have shown that leptin could substitute for insulin to control blood sugar fluctuations in patients with type 1 diabetes." (PMID 24639883, 2014). "Given that overweight patients with type 1 diabetes are already hyperleptinemic, the findings of this study suggest that the enhancement of leptin signaling in the hypothalamic ARC using liraglutide treatment may contribute to weight loss and improved glucose metabolism." (PMID 40429740, 2025). "In patients with newly diagnosed type 1 diabetes, the endogenous leptin levels are generally decreased, and they are also very low in patients with diabetic ketoacidosis but rise again after initiation of insulin therapy, possibly because of a direct effect of insulin on leptin release." (PMID 31743040, 2020). "Of note, the streptozotocin-induced type 1 diabetes model is characterized by more complex metabolic changes, including drastic decrease of insulin levels and alteration of leptin signalling, which may explain the differences between our in vivo and in vitro models." (PMID 32974347, 2020). "The secondary endpoint of the research was to analyze the impact of maternal age, duration of type-1 diabetes mellitus, BMI, HbA1c, TSH, leptin, and BDNF on neonatal overweight." (PMID 36771307, 2023). "The anti-steatosis action of leptin has been shown in non-obese mice with type I diabetes, whereby leptin administration led to significant reductions of lipogenic transcription factors and decreased plasma and tissue lipids." (PMID 36834959, 2023). "For example, leptin injection in a non-obese rodent model of type 1 diabetes, results in the normalization of blood glucose." (PMID 35454388, 2022). "In non-obese mice with type 1 diabetes, it was further shown that substitution of insulin with leptin or supplementation of leptin instead of insulin therapy can mimic the effect of insulin monotherapy." (PMID 33808424, 2021). "Our observations provide unambiguous evidence that the pituitary is not essential for leptin’s chronic CNS effects that can completely normalize plasma glucose concentration in rodents with type 1 diabetes." (PMID 29190687, 2017). "Furthermore, icv leptin delivery improves expression of the metabolically relevant hypothalamic neuropeptides POMC, NPY, and AgRP in type 1 diabetes mice." (PMID 23579596, 2013). "Thus, in contrast to traditional rodent models of type 1 diabetes, most patients with type 1 diabetes are not hypoleptinemic, and their sensitivity to leptin is therefore reduced." (PMID 31743040, 2020). "The relationship between insulin and leptin has been heavily studied, with findings most recently suggesting that leptin has an inhibitory effect on insulin secretion and reduces glucagon secretion in rodents with type 1 diabetes, resulting in improved glycemic control in the absence of insulin." (PMID 24987413, 2014). "Sincerepletion of the insulin deficiency that is presentin non-acidotic, ambulatory patients with newonset Type 1 diabetes did not alter serum leptin,these results argue against an effect of insulin onserum leptin in the absence of the acute diabeticketoacidosis." (PMID 12369715, 2001).
type 1 diabetes (continued). "Obese children with new onset type 1 diabetes are more likely to have higher pro-inflammatory markers (leptin, visfatin, chemerin, TNF-α, CRP) and lower anti-inflammatory markers (adiponectin, omentin) compared to non-obese peers with type 1 diabetes." (PMID 33828529, 2021).
cardiac hypertrophy (59 papers, 2012 to 2025). "Beyond its effects on cardiac hypertrophy and fibrosis, leptin has also been implicated in the pathophysiology of HFpEF by its potential to affect myocardial lusitropy, with complex mechanisms implicating calcium handling." (PMID 39682585, 2024). "In summary, this study confirmed that Plin5 deficiency promoted lactate accumulation due to excessive NADH production from FAO in cardiomyocytes, which impaired insulin signalling and resulted in myocardial hypertrophy in leptin-deficient mice." (PMID 37667357, 2023). "In this study, we found that lactate accumulation due to Plin5 deficiency aggravated myocardial hypertrophy in leptin-deficient mice." (PMID 37667357, 2023). "We also explored the roles and mechanism of Plin5 deficiency in the development of myocardial hypertrophy in leptin-deficient mice, which are characterized by abnormal lipid metabolism." (PMID 37667357, 2023). "Resistin and leptin promote cardiac hypertrophy, whereas leptin is also implicated in the regulation of cardiac contractility via a local nitric oxide dependent mechanism." (PMID 34948944, 2021). "Cardiovascular pathways associated with leptin included cardiac hypertrophy signaling and eNOS signaling." (PMID 31466225, 2019). "On the other hand, a deleterious effect of leptin on mitochondrial performance was described, which was also associated with the evolution of cardiac hypertrophy to heart failure." (PMID 30154842, 2018). "The leptin deficient mouse has impaired cardiac function after I/R injury in addition to higher cardiomyocyte death by apoptosis, ventricular hypertrophy and heart failure." (PMID 23028874, 2012). "Moreover, we found that Plin5 deficiency-induced lactate accumulation aggravated myocardial hypertrophy in leptin-deficient mice." (PMID 37667357, 2023). "We explored whether iron-regulating proteins are involved in cardiac hypertrophy, inflammation, and oxidative stress and whether CR confers benefits in leptin-deficient ob/ob and leptin-resistant db/db mice via regulation of iron homeostasis." (PMID 32346034, 2020). "Human and neonatal rat cardiomyocytes treated with recombinant leptin were more susceptible to progression of cardiac hypertrophy, as indicated by increased cell size, elevated matrix metalloproteinase-2 (MMP-2) activity, and endothelin-1-induced rise in ROS levels." (PMID 32655492, 2020). "Leptin signaling deficiency is correlated with a higher risk to onset of cardiac dysfunctions and heart failure: in obese mice, as leptin- or leptin receptor-deficient rodent models, elevated leptin concentrations induces cardiac hypertrophy, contractile and blood pressure abnormalities." (PMID 33171610, 2020). "In this line, leptin-deficient ob/ob and leptin-resistant db/db mice suffer from impaired cardiac function due to cardiac hypertrophy, inflammation, oxidative stress, and iron overload, an effect that is reverted by calorie restriction through the restoring of iron levels." (PMID 33081064, 2020). "Adiponectin and leptin also play an important role in regulating cardiac function and are linked to several cardiac pathophysiological conditions and diseases, particularly cardiac hypertrophy and heart failure." (PMID 31703113, 2019). "The presence of cardiac hypertrophy in LepR-deficient and, to a lesser extent also in diet-induced obese mice, suggests that it develops as a result of the heart’s inability to respond to elevated systemic and/or cardiac leptin levels." (PMID 23841921, 2013). "On the other hand and as confirmed in our analysis, cardiac hypertrophy also develops in leptin- and LepR-deficient mice and may be reversed by leptin substitution." (PMID 23841921, 2013). "Importantly, cardiac hypertrophy is also observed in normotensive obese subjects, and plasma leptin levels are associated with increased myocardial wall thickness independent of BW or blood pressure elevations, suggesting a causal role for leptin in the pathogenesis of cardiac hypertrophy." (PMID 23841921, 2013).